MEF2D (myocyte enhancer factor 2D)
Diseases named in the same sentence as MEF2D in open-access papers (continued):
Sharing a sentence is not in itself a finding about the gene and the disease.
migraine (11 papers, 2016 to 2025). "MEF2D, identified by GWAS hits for common migraine, has been linked to glutamatergic neurotransmission and neuron and synapse development." (PMID 38379763, 2024). "A subsequent Chinese replication study of 581 migraine cases and 533 ethnically matched controls identified three risk loci rs2274316 (MEF2D), rs6478241 (ASTN2) and rs2651899 (PRDM16) previously identified in European samples." (PMID 37245199, 2023). "HDAC4 encodes a Class IIa histone deacetylase, and along with co-repressors such as MEF2D encoded by a previously reported migraine GWAS locus, its activity targets lysine residues on core histone tails to repress transcription." (PMID 38087366, 2023). "Several genes (MTDH, LRP1, MEF2D) identified by GWAS hits for common migraine could also be linked to glutamate signalling, although these genes are not part of modules A or C." (PMID 26899160, 2016). "We further found the pathways “positive regulation of cytosolic calcium ion concentration” and “inositol phosphate-mediated signaling” and hub genes including MEF2D, TSPAN2, PHACTR1, TRPM8 and PRDM16 related to migraine susceptibility." (PMID 32046629, 2020). "Genetic associations (e.g., MEF2D, NLRP3) and comorbidities with autoimmune diseases—including multiple sclerosis (MS), rheumatoid arthritis (RA), systemic lupus erythematosus (SLE), and psoriasis—further support an immunological component in migraine." (PMID 40426647, 2025). "The lower expression level of MEF2D in brain regions with more ReHo increment in migraine may support the hypothesis that abnormalities in brain glucose metabolism generate a mismatch between the brain's energy reserve and metabolic expenditure, which may lead to ReHo increment in migraine." (PMID 38379763, 2024). "However, up till now, the potential role of TSPAN2 and MEF2D in migraine development still remains unknown." (PMID 32046629, 2020). "Interestingly, several common SNPs in the MEF2D gene have been reported to be strongly associated with migraine and blood cell phenotypes, but none of them have been implicated in association with any autoimmune disease." (PMID 30459414, 2019). "Among these shared genomic regions, those on chromosomes 1 and 9 harbour the MEF2D and ASTN2 genes, previously reported to be the closest genes to a lead migraine SNP and headache SNP." (PMID 36808568, 2023).
cardiac hypertrophy (9 papers, 2011 to 2025). "For example, the dysregulation of Mef2d has been implicated in conditions such as dilated cardiomyopathy and cardiac hypertrophy, reflecting shared inflammatory and metabolic axes." (PMID 40076622, 2025). "CRISPR-mediated endogenous activation of myocyte enhancer factor 2D (Mef2d) leads to cardiac hypertrophy in mice, indicating that CRISPR-mediated genome editing can be used to generate CVD mouse models by controlling transcription in the postnatal heart." (PMID 36895064, 2023). "The cardiac hypertrophy signaling pathway also identified the hypermethylated gene, myocyte enhancer factor 2D (MEF2D)." (PMID 35336913, 2022). "Our current study has provided several lines of evidence to support the notion that miR-92b-3p inhibits cardiac hypertrophy through targeting MEF2D." (PMID 29190899, 2017). "Next, we detected the expression of MEF2D in Ang-II-induced cardiac hypertrophy in vivo and in vitro." (PMID 29190899, 2017). "Further analysis of NF-AT3 and Mef2d, which both show altered DNA methylation patterns and are important factors during cardiac hypertrophy, is also warranted." (PMID 24475304, 2014). "Cardiac hypertrophy and CHD are mediated by transcription factor integration of upstream stress signals, and Mef2d-deficient mice have an attenuated hypertrophic response to cardiac stress." (PMID 22078008, 2011). "Taken together, our results suggested that the SUZ12(PRC2)-Mef2d axis could be critical in the regulation of cardiac hypertrophy by METTL5 mainly through modulating the translational efficiency of SUZ12 mRNA." (PMID 35295259, 2022). "Furthermore, MEF2a, MEF2c, and MEF2d are well characterized for their crucial roles in cardiac hypertrophy, and MEF2b has been implicated to play a role in cardiac development." (PMID 31532577, 2019). "MEF2a, MEF2c, and MEF2d have been demonstrated to play vital roles in cardiac hypertrophy." (PMID 31532577, 2019). "Our data suggest that MEF2D is a novel target of miR-92b-3p in myocardial hypertrophy, and enhancement of miR-92b-3p expression may be protective against myocardial hypertrophy." (PMID 29190899, 2017). "Taken together, we demonstrated that MEF2D is a novel target of miR-92b-3p, and attenuation of miR-92b-3p expression may contribute to the increase of MEF2D in cardiac hypertrophy." (PMID 29190899, 2017). "However, adult Mef2d knockout mice showed a reduced response to stress signals that would normally trigger cardiac hypertrophy and fibrosis, indicating MEF2D's activities are not entirely redundant." (PMID 26506234, 2016).
colorectal cancer (9 papers, 2017 to 2024). A primary or metastatic malignant neoplasm that affects the colon or rectum. "The myocyte enhancement factor mef2d promotes tumor angiogenesis in vitro and in vivo and induces the expression of pro-antigenic cytokines in colorectal cancer cells." (PMID 39705244, 2024). "MEF2D, for example, promotes epithelial-mesenchymal transition, metastasis, and angiogenesis in colorectal cancer." (PMID 34307695, 2021). "In colorectal cancer, MEF2D is a target gene of HIF1α, and MEF2D enhances transcriptional upregulation of proangiogenic cytokines." (PMID 33088284, 2020). "However, the overexpression of MEF2D has also been shown to induce the EMT in colorectal cancer, potentially through the transcriptional activation of ZEB1." (PMID 38791246, 2024). "The overexpression of MEF2D has been shown to promote invasion and the EMT in colorectal cancer cells." (PMID 38791246, 2024). "Previous studies have reported that MEF2D overexpression promotes EMT and metastasis in colorectal cancer." (PMID 38888512, 2024). "As an essential regulator of DCC fitness in the pro‐metastatic niche, MEF2D functions independent of regulating the EMT, a process observed in colorectal cancer cells detaching from the primary lesions." (PMID 37828611, 2023). "Unlike a role of MEF2D in enhancing growth and immune escape of HCC cells, and epithelial‐mesenchymal transition (EMT) of colorectal cancer cells, MEF2D promotes the spreading of HCC cells independent of regulating the EMT." (PMID 37828611, 2023).
gastric cancer (9 papers, 2011 to 2024). A primary or metastatic malignant neoplasm involving the stomach. "Furthermore, MEF2D has been implicated in the growth and metastasis of liver cancer, gastric cancer, and pancreatic cancer." (PMID 39719443, 2024). "It was also shown that miR-19 inhibits cell proliferation in gastric cancer by targeting Myocyte enhancer factor 2D (MEF2D)." (PMID 34722255, 2021). "The miR-19/MEF2D/Wnt/β-catenin axis is critical for gastric cancer cell survival and proliferation, suggesting miR-19 as a potential therapeutic target for gastric cancer." (PMID 27793042, 2017). "Previously we have shown that PKD2 can activate Mef2D in gastric cancer cells via phosphorylation of class II HDACs." (PMID 21298052, 2011). "In gastric cancer, MEF2D activates the Wnt/β-catenin pathway to promote invasion." (PMID 38888512, 2024). "Increased lncRNA H19 expression induces bortezomib resistance in multiple myeloma by upregulating MCL-1 via sponging miR-29b-3p LncR-D63785 acts as a competitive endogenous RNA of miR-422a and promotes chemotherapy resistance by blocking miR-422-dependent suppression of MEF2D in gastric cancer." (PMID 31581131, 2019). "MiR-19 inhibits cell proliferation in gastric cancer by targeting MEF2D." (PMID 27793042, 2017). "In particular, miR-200 targeted B-catenin, and miR-19 inhibited myocyte enhancer factor 2D (MEF2D) to block the Wnt pathway, while miR-133a-5p targeted TCF (which enhanced the transcription of oncogenes), thereby stopping cell proliferation in gastric cancer." (PMID 38675388, 2024).
osteosarcoma (9 papers, 2017 to 2024). A usually aggressive malignant bone-forming mesenchymal neoplasm, predominantly affecting adolescents and young adults. "Similar studies performed in osteosarcoma patients reveal that over-expression of MEF-2D and miR-30a leads to a tumor suppressor effect and suppresses osteosarcoma cell proliferation by inhibiting MEF-2D." (PMID 31105874, 2019). "The function of EPIC1 in osteosarcoma is conducted via promotion of MEF2D ubiquitylation." (PMID 32322669, 2020).
acute lymphoblastic leukemia (7 papers, 2013 to 2025). Leukemia with an acute onset, characterized by the presence of lymphoblasts in the bone marrow and the peripheral blood. "Interestingly however, oncogenic activity has been attributed to MEF2D fusion proteins in acute lymphoblastic leukaemia, underlining a broader role for MAPK7 signaling in oncogenesis." (PMID 26040563, 2015). "A role of DAZAP1 in transcription is also supported by the exclusion of DAZAP1 from the transcriptionally inactive XY bodies in pachytene spermatocytes and the fusion of DAZAP1 to the MEF2D oncogene in a pre-B acute lymphoblastic leukaemia, and warrants further investigation." (PMID 23965306, 2013). "MEF2D fusions are found in a special subtype of B-cell precursor acute lymphoblastic leukemia (BCP-ALL) with poor prognosis." (PMID 40695793, 2025). "High-resolution breakpoint mapping by Optical Genome Mapping enables precise detection of clinically actionable gene rearrangements in acute lymphoblastic leukemia (ALL), including MEF2D::CSF1R and PAX5::JAK2 fusions—hallmarks of the Philadelphia-like (Ph-like) ALL subtype." (PMID 41228238, 2025).
ovarian carcinoma (7 papers, 2017 to 2025). A malignant neoplasm originating from the surface ovarian epithelium. "In ovarian cancer, it has been reported that MEF2D expression is associated with cisplatin resistance." (PMID 38791246, 2024). "MEF2D is known to be overexpressed in ovarian cancer and is believed to contribute directly to chemotherapeutic resistance." (PMID 39341888, 2024). "In a public dataset, MEF2D and ZNF100 expression were both associated with ovarian cancer progression-free or overall survival time." (PMID 29029385, 2017). "We then examined genome-wide binding of MEF2D in SKOv3 ovarian cancer cells using ChIP-Seq." (PMID 35642638, 2022). "To examine the effects of variants on activity of the MEF2D promoter, we tested the effects of the four candidate outcome variants in MEF2D PRE1 on promoter activity in OVCAR8 and JAM cells, the two ovarian cancer cell lines in which MEF2D was most highly expressed." (PMID 29029385, 2017).
Parkinson disease (7 papers, 2016 to 2025). A progressive degenerative disorder of the central nervous system characterized by loss of dopamine producing neurons in the substantia nigra and the presence of Lewy bodies in the substantia nigra and locus coeruleus. "MEF2D is also linked to Parkinson’s disease through the cyclin-dependent kinase 5 (Cdk5), which directly phosphorylates MEF2D at Ser444." (PMID 36834528, 2023). "It has also been shown that MEF-2D has a neuro-protective ability with neurotoxicity associated with the MPTP in Parkinson's disease." (PMID 31105874, 2019). "Interestingly, GSEA also indicated LCNM+-enriched expression of genes that are regulated by several TFs—ATF4, EBF3, STAT3, and MEF2D—all of which are protective against Parkinson’s disease, or associated with NM content in dopamine cells of the substantia nigra." (PMID 41278831, 2025). "MEF-2D acts as a neuronal survival factor in the maintenance of dopaminergic neurons (DN), the progressive death of which leads to Parkinson's disease (PD)." (PMID 31105874, 2019). "Interestingly, the disruption of metabolism-related Mef2d was observed in mice and patients with Parkinson’s disease." (PMID 40076622, 2025). "The connection between MEF2D and Parkinson's disease started with the finding that cyclin dependent kinase 5 (Cdk5) directly phosphorylates MEF2D at Ser444 under stress conditions, which leads to an impairment of MEF2D transcriptional function." (PMID 27413575, 2016). "Numerous studies have associated all hub genes identified from downregulated DEGs with Alzheimer’s disease (AD) and other neurological conditions like dementia and Parkinson’s disease, e.g., NR4A3, which is involved in the regulation of the immune system or MEF2D, which has a neuroprotective role." (PMID 39766348, 2024).
breast carcinoma (6 papers, 2019 to 2025). "Taken together, these findings suggest that MEF2D is a TSG in breast cancer and that the loss of MEF2D induces cell transformation in vitro and tumor development in mice." (PMID 38791246, 2024). "The loss of MEF2D function induced a high-grade mammary tumor and malignant spindle cell proliferation." (PMID 38791246, 2024). "In this study, we explored whether MEF2D, a common upstream molecule, modulates known oncogenic signaling pathways associated with breast cancer." (PMID 38791246, 2024). "For instance, lncRNA CASC15 sustains breast cancer stemness through the miR-654-5p/MEF2D axis, while HAGLROS promotes tumor evolution via the miR-135b-3p/COL10A1 pathway and exosome-mediated macrophage polarization." (PMID 41614739, 2025). "The extent to which MEF2D inhibits the conversion of mammary epithelial cells into neoplastic cells and its functional significance in the initiation and progression of breast cancer are poorly understood." (PMID 38791246, 2024). "As expected, we found that a low expression of MEF2D was correlated with a worse overall and relapse-free survival in breast cancer patients." (PMID 38791246, 2024). "In the context of breast cancer, decreases in MEF2D mRNA levels have been observed in tumor samples, which is suggestive of a potential role of MEF2D as a tumor suppressor." (PMID 38791246, 2024). "We further analyzed the MEF2D mRNA expression levels in the TCGA breast cancer (BRCA) cohort using the UALCAN data analysis portal." (PMID 38791246, 2024). "In this regard, we identified several oncogenic signaling pathways that can be targeted, warranting further investigation in breast cancer tumors with deregulated MEF2D." (PMID 38791246, 2024). "The identification of potential TSGs, such as MEF2D, provides the opportunity to develop drugs that target specific driver genes in breast cancer." (PMID 38791246, 2024). "The MEF2D expression was significantly lower in triple-negative breast cancer (TNBC) cells compared with normal (MCF10A) or estrogen-receptor-positive (ER+) breast cancer cells." (PMID 38791246, 2024). "In summary, our findings indicated that the genetic perturbation of MEF2D led to the transformation of MECs in vitro and the development of mammary tumors in vivo." (PMID 38791246, 2024). "Next, to assess the effects of MEF2D on in vivo mammary-tumor-forming potential, sgMEF2D or sgControl cells were injected into the mammary fat pads of SCID mice." (PMID 38791246, 2024). "According to the cBioPortal The Cancer Genome Atlas (TCGA) database, 15%–21% of ovarian and breast cancers contained amplification and mRNA upregulation of MEF2D." (PMID 35642638, 2022). "Further investigation is warranted to determine whether MEF2D plays an essential role in chemotherapy resistance in breast cancer through the activation of YAP/TAZ signaling." (PMID 38791246, 2024). "Correspondingly, a reduced expression of MEF2D was observed in human triple-negative breast cancer cell lines, and a low MEF2D expression in tissue samples was found to be correlated with a worse overall survival and relapse-free survival in breast cancer patients." (PMID 38791246, 2024). "The present study evaluated whether the MEF2D transcription factor functions as a tumor suppressor in breast cancer." (PMID 38791246, 2024). "Furthermore, the low expression of MEF2D was correlated with a poor overall survival and recurrence-free survival in breast cancer patients." (PMID 38791246, 2024). "However, the direct role of MEF2D in breast cancer development and progression is poorly understood." (PMID 38791246, 2024). "Hence, this study provides compelling evidence supporting the role of MEF2D as a promising target for the development of new therapeutic strategies in not only breast cancer, but also other types of cancer." (PMID 38791246, 2024).
breast carcinoma (continued). "Finally, to determine whether MEF2D expression correlates with breast cancer patients’ outcomes, we analyzed the correlation between the MEF2D mRNA expression level and breast cancer patients’ survival using the Kaplan–Meier plotter." (PMID 38791246, 2024). "Because knockdown of AKT expression by RNAi was incomplete, it was not possible to rule out that SIK2 inhibition of AKT signaling might contribute to the enhancement of PARP inhibitor sensitivity in ovarian and breast cancers through a class-IIa HDACs/MEF2D–independent pathway." (PMID 35642638, 2022). "In the present study, we investigated the role of MEF2D in mammary epithelial cell (MEC) transformation and tumorigenesis and provided mechanistic insights into the dysregulation of MEF2D in breast cancer cells." (PMID 38791246, 2024).
glioma (6 papers, 2019 to 2024). A benign or malignant brain and spinal cord tumor that arises from glial cells (astrocytes, oligodendrocytes, ependymal cells). "MEF2D tumour‐associated activity could be suppressed by miR‐421 in gliomas." (PMID 34109727, 2021). "But the results of our study validated that Ser251 was a crucial functional site of MEF2D in glioma cells." (PMID 34109727, 2021). "In addition, miR-760 was reported to play the action of anti-tumor in glioma via targeting MEF2D." (PMID 37588107, 2023). "Interestingly, miR-760 and MEF2D are also involved in lncRNA LOC730100- and lncRNA DLEU1-mediated ceRNETs in glioma cells, respectively, implying the potential crosstalk between the circCPA4 and the lncRNAs." (PMID 33995499, 2021).
liver cancer (5 papers, 2014 to 2024). An epithelial or non-epithelial malignant neoplasm that arises from the liver. "Here, systemic motif‐enrichment identified myocyte enhancer factor 2D (MEF2D) as a critical sensor of niche signals to regulate DCCs adhesion and colonization, leading to intrahepatic metastasis and recurrence of liver cancer." (PMID 37828611, 2023). "In human liver cancers, MEF2D expression was correlated with FAK signatures, while inhibition of either MEF2D or FAK downregulated a panel of genes essential for cell adhesion and metastasis." (PMID 37828611, 2023). "Several studies reported p300 can induce the expression of PD-L1 in liver cancer to impair CD8+ T cell-mediated anti-tumor immunity, probably via acetylation of myocyte enhancer factor 2D (MEF2D)." (PMID 34880761, 2021). "Moreover, in liver cancer, the effects of SIRT7 on the efficacy of the checkpoint inhibitor were found to be dependent on MEF2D." (PMID 39719443, 2024).
pancreatic cancer (5 papers, 2019 to 2024). "By functional CRISPR‐screening, we identified USP14, a mediator of liver metastasis of pancreatic cancer, as a key regulator of MEF2D deubiquitination and stabilization." (PMID 37828611, 2023). "Of note, the increased expression of MEF2D is associated with tumour size, histological differentiation and TNM stage among pancreatic cancer patients." (PMID 34109727, 2021). "MEF2D regulates cell proliferation, migration and invasion abilities in pancreatic cancer via Akt/GSK‐3β signalling pathway." (PMID 34109727, 2021). "Increased MEF2D expression exists in pancreatic cancer tissues compared with adjacent normal tissues." (PMID 34109727, 2021).